DYRK1A (dual specificity tyrosine phosphorylation regulated kinase 1A)
Diseases named in the same sentence as DYRK1A in open-access papers (continued):
Sharing a sentence is not in itself a finding about the gene and the disease.
dementia (11 papers, 2014 to 2023). Loss of intellectual abilities interfering with an individual's social and occupational functions. "However when stratifying with PiB-PET SUVR, the group with low Aβ had significantly higher DYRK1A than the group with high Aβ, indicating that individuals with low DYRK1A are potentially at-risk for dementia-associated pathologies such as brain Aβ deposition." (PMID 37015911, 2023). "In addition, lower DYRK1A levels were present in AD and in other dementia-associated pathologies, including frontotemporal lobar degeneration, hippocampal sclerosis, or progressive supranuclear palsy/corticobasal degeneration." (PMID 37015911, 2023). "It is believed that DYRK1A may “play a significant role in developmental brain defects, and in the early onset of neurodegeneration neuronal loss and dementia in T21”." (PMID 37808474, 2023). "Genetically, SNCA (α-synuclein gene) duplications, SNCA Rep1 microsatellites, and SNCA polymorphism contribute to the cognitive impairments and dementia in PD, and DYRK1A polymorphisms, which encode a kinase that phosphorylates α-synuclein, are associated with dementia in PD." (PMID 30958793, 2019). "If DYRK1A is a significant risk factor for AD, extra DYRK1A expression in T21/AD even over AD without T21 could explain or at least contribute to the much earlier onset of pathology and dementia in T21 individuals." (PMID 37808474, 2023). "DYRK1A is an important factor that contributes to intellectual disability, memory deficit, and AD-type dementia, the main characteristics of the DS phenotype." (PMID 35740400, 2022). "Overexpression of human DYRK1A, amyloid-β and Tau 0N4R occurs throughout development and adulthood leading to AD-DS pathology and dementia in young adults." (PMID 35928283, 2022). "As a result of life-long overexpression of the APP and DYRK1a genes, DS individuals suffer from AD-related dementia in the vast majority of the cases over 40y." (PMID 30389461, 2019). "The finding of increased DYRK1A expression in the brain of AD patients without DS suggested that DYRK1A is involved in the pathogenesis of neurodegeneration and dementia associated with this disease." (PMID 37900285, 2023). "Our results show that the comparison between full-length and truncated-form levels of DYRK1A coupled with ADNP levels could be used in trials targeting pathophysiological mechanisms of dementia in individuals with DS." (PMID 35740400, 2022). "Targeting DYRK1A appears to be a doable treatment approach for AD and dementia." (PMID 36012629, 2022). "In conclusion, this study shows for the first time that the comparison between full-length and truncated form levels of DYRK1A coupled with ADNP levels could be used in trials targeting pathophysiological mechanisms of dementia in individuals with DS." (PMID 35740400, 2022). "Increased plasma DYRK1A levels with aging may exert an anti-inflammatory effect at the beginning of the neuropathological process, thus delaying early signs of neurodegeneration and dementia." (PMID 37015911, 2023). "Contrasting with underexpression in normal brain described in the present study, DYRK1A overexpression is a central point for the deregulation of multiple pathways in the developing and aging DS brain, with structural and functional alterations including mental retardation and dementia." (PMID 25767303, 2014). "Lymphoblastoid cell lines established from lymphocytes of individuals with DS without dementia (DS), individuals with DS and with dementia (DSAD), and age-matched controls were grown in standard medium, and proteins were isolated to quantify DYRK1A." (PMID 37015911, 2023). "Our work suggests that the critical point for dementia is not DYRK1A levels alone but a ratio between the levels of DYRK1A and another HSA21 gene that we call X. High DYRK1A/X ratio may delay onset of AD-type dementia in DS." (PMID 37015911, 2023).
Mental Retardation autosomal Dominant 7 (11 papers, 2016 to 2024). "Patients with the DYRK1A pathogenic variant show “mental retardation, autosomal dominant 7” (MIM #614104), which is also called DYRK1A-related intellectual disability syndrome." (PMID 34253714, 2021). "Haploinsufficiency of DYRK1A is a cause of a neurodevelopmental syndrome termed mental retardation autosomal dominant 7 (MRD7)." (PMID 29700199, 2018). "Decreased expression due to haploinsufficiency of DYRK1A is also pathogenic and causes a developmental syndrome termed mental retardation autosomal dominant 7 (MRD7) (OMIM 614104)." (PMID 29700199, 2018). "Autosomal dominant mental retardation 7 (MRD7), or DYRK1A‐Related Intellectual Disability Syndrome (OMIM 614104), results from de novo variants in, or structural rearrangements that overlap the DYRK1A locus." (PMID 33159716, 2020).
ovarian carcinoma (11 papers, 2012 to 2025). A malignant neoplasm originating from the surface ovarian epithelium. "In epithelial ovarian cancer, inhibiting DYRK1A via siRNA knockdown or CDK inhibition compromised the DREAM complex and enhanced the viability of ovarian cancer cell spheroids." (PMID 39796178, 2025). "DYRK1A was previously discovered to support survival of ovarian cancer cells in suspension culture." (PMID 39023520, 2024). "It appears that the DYRK1A protein again plays a major role in the manifestation of these diseases as its modulation in sarcoma, and lung, pancreatic, and ovarian cancer may result in dysregulation of cell cycle control." (PMID 36012629, 2022). "Moreover, this kinase mediates the DREAM complex assembly leading to ovarian cancer dormancy as DYRK1A inhibition reduced spheroid viability and restored sensitivity to chemotherapy and targeting actively proliferating cells." (PMID 36012629, 2022). "Notably, DYRK1A-mediated DREAM complex formation was proposed to be responsible for ovarian cancer cell dormancy and for the quiescence of gastrointestinal stromal tumor (GIST) cells induced by treatment with imatinib." (PMID 32751160, 2020). "Finally, the synthetic DYRK1A inhibitor INDY, proven to modulate the phenotypic effects of DYRK1A overexpression in vivo, has been shown to improve the response of ovarian cancer spheroids to carboplatin." (PMID 32751160, 2020). "Spheroids of epithelial ovarian cancer (EOC) cells depended on the dimerization partner, RB-like, E2F and multi-vulval class B (DREAM) repressor complex induced by dual specificity tyrosine-phosphorylation-regulated kinase 1A (Dyrk1A)." (PMID 38835346, 2024). "In cell models, DYRK1A knockdown or enzymatic inhibition reduced the proliferation of HNSCC cell lines, luminal/HER2 breast cancer or PDAC, as well as impaired the self-renewal capacity of GBM cells and compromised ovarian cancer spheroid cell viability." (PMID 32751160, 2020). "Indeed, recent studies have reported that genetic knock-out of the DYRK1A gene sensitizes CRC cells to topotecan, an anti-tumor drug similar to irinotecan in chemical structure and mechanism of action, commonly used to treat ovarian cancer." (PMID 39896677, 2025).
acute myeloid leukemia (10 papers, 2017 to 2025). Acute myeloid leukemia (AML) is a group of neoplasms arising from precursor cells committed to the myeloid cell-line differentiation. "DYRK1A is associated with oncogenic protein inactivation and cell cycling in acute myeloid leukemia (AML)." (PMID 33804169, 2021). "It was previously shown that DYRK1A phosphorylates c-Myc in acute myeloid leukemia (AML), and Cyclin D3 in pre-B cells to enhance their degradation." (PMID 36927854, 2023). "In contrast, another study showed that DYRK1A could act as a tumour suppressor by downregulating c-Myc in acute myeloid leukaemia cells." (PMID 35655269, 2022). "Changes in the DYRK1A expression have been analyzed in tumor samples, and as such, DYRK1A was seen to be downregulated in breast cancer and in acute myeloid leukemia (AML) tissue, and it is upregulated in GBM, lung cancer and head and neck squamous cell carcinoma (HNSCC), as well as in PDAC." (PMID 32751160, 2020). "Experimental studies confirm that DYRK1A is associated with acute lymphocytic leukemia (ALL), acute myeloid leukemia (AML) and breast cancer (BRCA)." (PMID 38459430, 2024). "A previous report also found that DYRK1A inhibited the proliferation and chemosensitivity of acute myeloid leukemia (AML) cell lines through downregulation c-Myc30." (PMID 28623290, 2017). "Contrary to pediatric DS-AMKL, in acute myeloid leukemia (AML) cells from euploid adults, DYRK1A could exert a tumor suppressor function." (PMID 40519271, 2025). "This scenario parallels the mechanism of the antiproliferative role of DYRK1A in acute myeloid leukemia (AML) cells, where DYRK1A overexpression accelerates c-MYC degradation without affecting mRNA levels." (PMID 39482615, 2024).
intellectual disability syndrome (10 papers, 2020 to 2025). "We further found that numerous mutation sites relevant to the DYRK1A-related intellectual disability syndrome locate in the C-terminal of HsDYRK1A." (PMID 36830653, 2023). "One hundred and eight DYRK1A variants have been reported to cause DYRK1A-related intellectual disability syndrome, 75% are single nucleotide variants (81/108), with 17 being novel from this study." (PMID 33562844, 2021). "By increasing the awareness of the ocular associations of DYRK1A-related intellectual disability syndrome, a consensus on disease associations can be established, leading to more research into pathological mechanisms." (PMID 33562844, 2021). "From this gathered cohort it is suggested that patients with DYRK1A-related intellectual disability syndrome are at an increased risk of developing both these features." (PMID 33562844, 2021). "Due to the rarity of DYRK1A‐Related Intellectual Disability Syndrome, the spectrum of symptoms associated with this disease has not been completely defined." (PMID 33159716, 2020). "However, one study expanded the phenotype of DYRK1A-related intellectual disability syndrome (caused by mutations or deletions in DYRK1A) to include CAKUT." (PMID 40149397, 2025). "We report a case of DYRK1A-related intellectual disability syndrome caused by a novel mutation." (PMID 39109359, 2024). "Moreover, many nonsense or missense mutations that occurred in the activation domain of HsDYRK1A are associated with the DYRK1A-related intellectual disability syndrome." (PMID 36830653, 2023). "This study highlights that patients with DYRK1A-related intellectual disability syndrome may be at an increased risk of developmental ocular pathology compared to the general population, particularly optic nerve hypoplasia, refractive error and strabismus." (PMID 33562844, 2021). "Patients exhibited features of DYRK1A-related intellectual disability syndrome, which include autism, microcephaly, developmental delay, seizures, and others." (PMID 40149397, 2025). "The DYRK1A gene plays a crucial role in central nervous system development, with haploinsufficiency leading to DYRK1A-related intellectual disability syndrome." (PMID 40405340, 2025). "All these mutations cause characteristic features that define a well-recognizable syndrome of ID/ASD known as MRD7 (Mental Retardation Dominant 7, OMIM: 614104) or DYRK1A-intellectual disability syndrome (DYRK1A syndrome for short, ORPHA: 464306)." (PMID 36402907, 2022). "In this gathered cohort of DYRK1A-related intellectual disability syndrome, 32 patients described refractive error." (PMID 33562844, 2021). "Further research into this pathophysiology will improve our understanding of the neuropathology of optic nerve hypoplasia in patients with DYRK1A-related intellectual disability syndrome." (PMID 33562844, 2021). "Ventricular enlargement has already been reported in a patient with DYRK1A-related intellectual disability syndrome." (PMID 34253714, 2021). "This variant is novel, but the same amino acid change (c.957C>A, p.Tyr319*) has previously been reported in DYRK1A-related intellectual disability syndrome." (PMID 34253714, 2021). "Epileptic events and data from magnetic resonance imaging (MRI) assessments have been reported for patients with DYRK1A-related intellectual disability syndrome; however, the clinical course is not well understood." (PMID 34253714, 2021). "The result showed that there were many mutations locating in the HsDYRK1A activation domain that might be involved in DYRK1A-related intellectual disability syndrome." (PMID 36830653, 2023). "DYRK1A-related intellectual disability syndrome is characterised by a broad syndromic phenotype." (PMID 33562844, 2021). "The clinical course of epilepsy in patients with DYRK1A-related intellectual disability syndrome may be well controlled." (PMID 34253714, 2021). "DYRK1A-related intellectual disability syndrome is a rare disease." (PMID 33562844, 2021).
intellectual disability syndrome (continued). "Our patient’s clinical manifestations, consisting of physical and facial features as well as developmental and neuropsychiatric features, were compatible with the clinical manifestations observed in patients with DYRK1A-related intellectual disability syndrome." (PMID 34253714, 2021).
tauopathies (10 papers, 2011 to 2026). "Collectively, the present results indicate that DYRK1A plays an important role in cognitive function, Aβ/tauopathy and neuroinflammation in WT mice and mouse models of AD, implicating DYRK1A as a potential therapeutic target for AD." (PMID 41306975, 2025). "Taken together, our data indicate that DYRK1A modulates cognitive function, neuroinflammation, and AD pathology (Aβ and tauopathy) in mouse models of AD and/or WT mice and support DYRK1A as a potential therapeutic target for AD." (PMID 41306975, 2025). "We also compared levels of plasma DYRK1A from patients with various tauopathies in the SHATAU7-IMATAU cohort: frontotemporal lobar degeneration, hippocampal sclerosis, and progressive supranuclear palsy and corticobasal degeneration." (PMID 37015911, 2023). "However, pharmacological DYRK1A inhibition significantly reduces tauopathy in 3xTg mice, a mouse model of AD exhibiting both Aβ pathology and tauopathy." (PMID 41306975, 2025). "Low DYRK1A levels were also detected in patients with tauopathies." (PMID 37015911, 2023). "Moreover, varlitinib more effectively inhibits tau-induced gliosis, tau phosphorylation and tau kinase DYRK1A expression in the early stage of tauopathy than in the middle stage of tauopathy in tau-overexpressing PS19 mice." (PMID 36341365, 2022). "It is hypothesized that inhibition of DYRK1A activity may reduce tau pathology and inflammation and thus prevent, slow, or reverse AD or other chronic tauopathies." (PMID 31267651, 2019). "However, the dual Dyrk1A/Clk1 inhibitory activity might even provide higher efficacy for the treatment of tauopathies, because both kinases are modifying the pre-mRNA splicing to generate tau species with enhanced pathogenic potential." (PMID 24676346, 2014). "However, beyond these findings, the effect of direct genetic inhibition of DYRK1A in the brain on tauopathy has not been fully investigated in mouse models of AD." (PMID 41306975, 2025). "Thus, we assessed whether varlitinib can reduce tauopathy and found that varlitinib significantly decreased tau phosphorylation at Thr212/Ser214 and Thr231 (AT180) as well as tau kinase DYRK1A levels in 3-month-old PS19 mice." (PMID 36341365, 2022).
pancreatic cancer (9 papers, 2016 to 2024). "The TCGA (PAAD) and GTEx (Pancreas) databases indicated that the DYRK1A expression level was significantly higher in pancreatic cancer than in the corresponding normal pancreas tissue." (PMID 35053488, 2022). "DYRK1A expression is relatively widespread, while specific cases of ovarian and pancreatic cancer possess amplification of the DYRK1B gene and dependence on it rather than DYRK1A." (PMID 35321751, 2022). "Therefore, we focused on the role of DYRK1A in the radiotherapy of pancreatic cancer in the following experiments." (PMID 35053488, 2022). "To demonstrate that DYRK1A may be exploited as a target for improved radiation therapy in pancreatic cancer, we used two separate sgRNAs to knock out the DYRK1A gene in TB32047 and MIA PaCa-2 cells and generated totally knocked out single clone cells." (PMID 35053488, 2022). "On the other hand, DYRK1A was highly expressed in lung and pancreatic cancer cells, and that its protein level was positively correlated with that of STAT3, c-MET and EGFR as it was found that DYRK1A siRNA could suppress the levels of EGFR and MET receptor tyrosine kinases." (PMID 36012629, 2022). "In similar studies inhibiting DYRK1A with Harmine improved the efficacy of Imatinib in clearing gastrointestinal cancer in mice, while DYRK1B inhibition combined with Gemcitabine was shown to improve pancreatic cancer cell killing in vitro." (PMID 37608096, 2023). "Our results demonstrated that knockout DYRK1A in PC cell lines might result in increased DNA damage and impaired HRR after DSBs, hence decreasing radioresistance in pancreatic cancer." (PMID 35053488, 2022). "In agreement with the previous data in SUFU-deficient and pancreatic cancer cells, inhibition of DYRK1B but not of DYRK1A reduced GLI1 protein levels." (PMID 26784250, 2016). "In agreement with the critical role of DYRK1B in GLI1 expression, RNA-interference against DYRK1B but not against DYRK1A inhibited clonogenic growth of GLI1-dependent pancreatic cancer cells." (PMID 26784250, 2016). "Moreover, the role of DYRK1A in the radioresistance of pancreatic cancer has not been reported." (PMID 35053488, 2022).
epilepsy (8 papers, 2008 to 2024). A brain disorder characterized by episodes of abnormally increased neuronal discharge resulting in transient episodes of sensory or motor neurological dysfunction, or psychic dysfunction. "In contrast, recurrent disruptive mutations in DYRK1a are correlated with a range of intellectual disability disorders with associated epilepsy." (PMID 39305956, 2024). "Finally, as DYRK1A haploinsufficiency in human is causing epilepsy, we challenged the homozygous inactivation in Dyrk1aC/C and control mice with two different doses of the seizure-provoking agent pentylenetetrazol (PTZ) and the occurrence of myoclonic, clonic and tonic seizures was scored." (PMID 34587162, 2021). "Another important mTOR regulator involved in epilepsy is dual specificity tyrosine-phosphorylation-regulated kinase 1A (DYRK1A), an inhibitor of mTORC1." (PMID 36982355, 2023). "Epilepsy and white matter abnormality have been reported in DYRK1A-related intellectual disability syndrome; however, the clinical course has yet to be elucidated." (PMID 34253714, 2021). "In addition, mental retardation, autosomal dominant 7 (MRD7) patients with Dyrk1a haploinsufficiency display epilepsy seizures." (PMID 30115750, 2018).